TAB2 (TGF-beta activated kinase 1 (MAP3K7) binding protein 2)
Diseases named in the same sentence as TAB2 in open-access papers (continued):
Sharing a sentence is not in itself a finding about the gene and the disease.
cancer (12 papers, 2010 to 2025). A tumor composed of atypical neoplastic, often pleomorphic cells that invade other tissues. "Aberrant expression and function of TAB2 have been implicated in the development and progression of various cancers." (PMID 40133221, 2025). "Using CC cell lines and established cisplatin‐resistant variants, we demonstrated that TAB2 regulates multiple aspects of cancer cell behaviour including stemness properties, cell growth, migration and immune escape." (PMID 40133221, 2025). "Aberrant expression of TAB2 protein is significantly associated with cancer progression through activation of mitogen-activated protein kinase (MAPK) and NF-κB signaling pathway." (PMID 34900737, 2021). "Our findings demonstrate that TAB2 modulates multiple aggressive cancer phenotypes, including enhanced cell proliferation, increased migration capacity and pronounced stemness characteristics, all through NF‐κB signalling activation." (PMID 40133221, 2025). "This is supported by other research demonstrating the role of NF‐κB activation in upregulating PD‐L1 in various cancers, and the involvement of miRNAs like miR‐149‐5p in regulating inflammation and immune responses via TAB2." (PMID 40133221, 2025). "To evaluate the functional significance of this TAB2‐NF‐κB‐PD‐L1 axis, we assessed cancer cell sensitivity to T cell‐mediated killing." (PMID 40133221, 2025). "Second, the potential role of TAB2 in regulating other cancer‐related pathways warrants exploration." (PMID 40133221, 2025). "Our previous results demonstrated that TAB2 promotes cancer stemness through NF‐κB pathway activation, as evidenced by enhanced sphere formation capacity and increased expression of stem cell markers SOX2 and BMI1." (PMID 40133221, 2025). "Our study demonstrates that TAB2 coordinates multiple aspects of cancer progression through NF‐κB signalling." (PMID 40133221, 2025). "IL-6/JAK/STAT3 pathway is predicted to be activated in TAb2 tumors, which is often hyperactivated in various types of cancer that correlates with poor prognosis." (PMID 35366939, 2022). "Because TAB2 is of great importance to regulate cancer stem cells, we analyzed the prognostic potential of it in CC." (PMID 34306095, 2021). "It is found that transforming growth factor β-activated kinase 1 binding protein 2 (TAB2) was significantly upregulated in Siha-derived cancer stem-like cells." (PMID 34306095, 2021). "Although further research is needed to uncover the carcinogenic mechanisms of TAB2, our current study lays the foundation for developing better treatment strategies in human cancers." (PMID 34306095, 2021). "To investigate whether TAB2 regulates cancer stemness through NF‐κB signalling, we overexpressed TAB2 in Siha and MS751 cells with or without the NF‐κB inhibitor BAY 11–7082." (PMID 40133221, 2025). "Furthermore, TAB2 has been found to promote the development and progression of CC by regulating the properties of cancer stem cells (CSCs)." (PMID 40133221, 2025). "Based on the established role of NF‐κB signalling in promoting cancer cell stemness and chemoresistance, and our findings that TAB2 activates the NF‐κB pathway in CC cells, we hypothesised that TAB2 might regulate chemoresistance." (PMID 40133221, 2025). "However, despite these findings suggesting an important role for TAB2 in certain cancers, the specific role and mechanisms of TAB2 in CC, and how it interacts with other signalling pathways, such as NF‐κB, remain poorly understood." (PMID 40133221, 2025). "Since TRAF2, IKBKB, and TAB2 proteins are directly or indirectly involved in NFκB activation, the influence of these proteins on tumorigenesis is discussed in many studies related to cancer occurrence." (PMID 39061149, 2024). "Moreover, the regulatory mechanism of TAB2 in cancer stem cells (CSCs) is related to promoting the malignant transformation and invasiveness of CC, which is a prognostic marker of CC52." (PMID 36202899, 2022).
cancer (continued). "Moreover, transforming growth factor β binding activated kinase 1 protein 2 (TAB2) is an inflammatory mediator in cancer pathogenesis." (PMID 34900737, 2021). "Meanwhile, lower protein expression of SOCS1 and Foxp3 was only evident in both cachectic cancer groups without any association between TAB2 protein expression and the presence of cachexia." (PMID 34900737, 2021). "We carried out the following experiments to investigate whether miR‐7/TAB2 axis was responsible for circ‐WHSC1‐induced cancer progression." (PMID 34551195, 2021). "Furthermore, TAB2 was responsible for the cancer progression induced by circ‐WHSC1." (PMID 34551195, 2021). "CYLD and SMPD2 were characteristics of G2 cancer, and TNFR1, TNFR2, NFKB1, TAB2, and USP4 for G3 cancer." (PMID 37233761, 2023). "Correlation analysis between miR-155 gene expression and SOCS1, TAB2, and Foxp3 in cachectic pancreatic or NSCL cancer patients (Spearman’s correlation)." (PMID 34900737, 2021). "Expression level of miR-155, SOCS1, TAB2, and Foxp3 in cancer cachectic patients considering the cachexia severity, regardless of the cancer type." (PMID 34900737, 2021). "Finally, the involvement of SOCS1, TAB2, and Foxp3 as direct targets for TNF-α gene in both cancer types was assessed." (PMID 34900737, 2021). "While other TAB partners of TAK1, namely TAB2 or TAB3, may be involved in the regulation of TAK1 activity in other chronic conditions such as cancer, our focus remains on TAK1/TAB1 complex given its established role in IL-1β-induced TAK1 activation in human RASFs." (PMID 36032089, 2022). "Serum SOCS1, TAB2, and Foxp3 level in cachectic and non-cachectic pancreatic and NSCL cancer patients and cachexia severity." (PMID 34900737, 2021).
infection (9 papers, 2012 to 2024). The state of being infected such as from the introduction of a foreign agent such as serum, vaccine, antigenic substance or organism. "In the spleen, the change in TAB2 gene expression was observed only during infection with the GI.1 genotype (1.8-fold change (p = 0.04) compared to the control)." (PMID 39273479, 2024). "Consistently, compared with the control, the expression levels of both imd and Tab2 are also significantly down-regulated in flies with high-expressed miR-277 at 3 h, 6 h and 12 h post infection, respectively." (PMID 32810129, 2020). "Meanwhile, MY1ΔsipC infection had no influence in the mRNA expression of inflammatory gene regardless of TAB2 knockdown or overexpression." (PMID 31565575, 2019). "Although our in vivo data suggested miR-155 contributed to Tab2 downregulation in microglia during infection, they also showed it was not solely responsible for this finding." (PMID 30538705, 2018). "Furthermore, tandem mass spectrometric analysis of TAB2/3 from infected 293T cells confirmed the methylation modification as a Cys673-methylated peptide from Flag-TAB2 was detected upon infection with wild-type EPEC but not the ΔnleE strain." (PMID 25412445, 2014).
bacterial infection (2 papers, 2014 to 2023). "More recently, a novel role for S-methylation has been suggested for regulating the ubiquitin chain-sensing functions of TGF-β-activated kinase-binding proteins TAB-2/3 in the NF-kB signaling pathway in response to bacterial infection." (PMID 24235145, 2014). "Overall, shrimp Toll1/2/3/5/9–TRAF6/TAB2/TAK1–Dorsal cascades protect the host from V. parahaemolyticus infection, which provides a better understanding of how the innate immune system recognizes and responds to bacterial infections in invertebrates." (PMID 36817428, 2023).
heart disease (2 papers, 2018 to 2021). "TAB2 (TAK1 binding protein-2) is known to play an important role in cardiac development and has recently received more attention in heart diseases." (PMID 34408773, 2021).
kidney disease (1 paper, 2024). "In addition, differential expression of TGF-beta-activated kinase 1 and MAP3K7-binding protein 2 (Tab2, involving renal inflammation and injury) are predicted to be associated with kidney disease." (PMID 38814931, 2024). "Overexpression of Tab2 is associated with the leaky-gut molecule (soluble CD14) and also plays a key role in kidney disease via translocation of uremic toxins such as p-cresyl and indoxyl that promote CKD." (PMID 38814931, 2024).
neurodevelopmental disorder (1 paper, 2021). A behavioral and cognitive disorder with onset during the developmental period that involves impaired or aberrant development of intellectual, motor, or social functions. "Other highly enriched genes for nsDNV—KMT2D (OMIM 147920), KMT2A (OMIM 605130), NSD1 (OMIM 117550), TAB2 (OMIM 614980), and ADNP (OMIM 615873)—have been previously associated with different types of neurodevelopmental disorders with co-occurrence of CHD." (PMID 34324492, 2021).
TAB2 also shares sentences with these, for which no sentence is quoted: frontometaphyseal dysplasia (3 papers); colitis (2); rheumatoid arthritis (2); acute kidney injury (1); age-related macular degeneration (1); Alzheimer disease (1); Cachexia (1); cardiovascular diseases (1); Cerebral ischemia (1); chronic kidney disease (1); congenital heart malformations of (1); congestive heart failure (1); diabetes (1); Hodgkins lymphoma (1); Hypertension (1); Immune Deficiency (1); intrauterine growth restriction (1); leishmaniasis (1); Oral Cancer (1); otopalatodigital syndrome spectrum disorder (1); ovarian cancer (1); primary ciliary dyskinesia (1); steatosis (1).